CALML4 (calmodulin like 4)
Description:
As part of the intermicrovillar adhesion complex/IMAC plays a role in epithelial brush border differentiation, controlling microvilli organization and length. Acts as a light chain for MYO7B and is required for efficient targeting of the IMAC to the tips of border brush microvilli.
Synonyms: MGC4809; NY-BR-20
Tractability: No criterion of Open Targets' tractability assessment is met for any kind of drug.
Gene: Protein-coding gene on chromosome 15 (68,190,705 to 68,206,087, reverse strand). Ensembl gene ENSG00000129007.
Subcellular location: Cell projection, microvillus (Isoform 1); Cell projection, microvillus (Isoform 6)
Subcellular location (Human Protein Atlas): Golgi apparatus; Cytosol; Nucleoplasm
Gene Ontology:
Molecular function: myosin head/neck binding; enzyme regulator activity; calcium ion binding
Biological process: brush border assembly; microtubule cytoskeleton organization
Cellular component: microvillus
Genetic constraint (gnomAD): Loss-of-function variants: 15 observed, 16.8 expected, observed/expected ratio (o/e) 0.89, 90% interval 0.6 to 1.37. The upper end of that interval is the gene's LOEUF score, 1.37, which puts it in group 5 of 6, group 1 being the genes least tolerant of losing a copy. Missense variants: 166 observed, 170.92 expected, observed/expected ratio (o/e) 0.97, 90% interval 0.86 to 1.11. Synonymous variants: 73 observed, 63.36 expected, observed/expected ratio (o/e) 1.15, 90% interval 0.95 to 1.4.
Homologues: Orthologues: chimpanzee CALML4 (98% identical), mouse Calml4 (86% identical), rat Calml4 (86% identical), pig CALML4 (82% identical), guinea pig CALML4 (76% identical), dog CALML4 (67% identical), zebrafish calml4a (65% identical), tropical clawed frog calml4 (61% identical), zebrafish calml4b (51% identical), Drosophila melanogaster CG17272 (35% identical), Caenorhabditis elegans cal-3 (29% identical), Caenorhabditis elegans cal-1 (29% identical), and 4 more. Paralogues in human: CALM1 (42% identical), CALM2 (42% identical), CALM3 (42% identical), CALML3 (39% identical), CETN1 (33% identical), CETN2 (33% identical), CABP5 (29% identical), CALML6 (29% identical), CABP1 (28% identical), CABP2 (28% identical), CETN3 (28% identical), CABP4 (26% identical), and 8 more.
Diseases named in the same sentence as CALML4 in open-access papers:
CALML4 is named in the same sentence as 11 diseases in open-access papers, as found by Europe PMC text mining. Sharing a sentence is not in itself a finding about the gene and the disease. The quoted sentences say what the papers report.
Alzheimer disease (2 papers, 2023 to 2025). A progressive, neurodegenerative disease characterized by loss of function and death of nerve cells in several areas of the brain leading to loss of cognitive function such as memory and language. "Beyond established biomarkers, we identify CALML4 (calmodulin-like 4) as a potential novel biomarker for Alzheimer’s disease (AD)." (PMID 40076442, 2025). "Among the MNPs@FMN‐altered DEGs, ubiquinol cytochrome c reductase binding protein (Uqcrb), cytochrome C oxidase subunit 8b (Cox8b), and calmodulin‐like protein 4 (Calml4) were enriched in the “Alzheimer's disease” pathway." (PMID 36799538, 2023).
depression (1 paper, 2021). "After LBRD standard decoction administration, four differentially expressed miRNAs, rno-miR-144-3p, rno-miR-495, rno-miR-34c-5p, and rno-miR-24-3p, and six differentially expressed mRNAs, Calml4, Ntrk2, VGAT, Gad1, Nr1d1, and Bdnf overlapped in the in vivo/vitro depression model." (PMID 34674715, 2021).
gastric cancer (1 paper, 2025). A primary or metastatic malignant neoplasm involving the stomach. "In previous studies, highly expressed CALML4 was reported as activating CGMP-PKG signaling pathway and suppressing tumors in gastric cancer." (PMID 40872572, 2025).
glioma (1 paper, 2021). A benign or malignant brain and spinal cord tumor that arises from glial cells (astrocytes, oligodendrocytes, ependymal cells). "High expressions of CALD1, CALML4, CALML6, CALM1 and CALM2 were associated with IDH wildtype glioma." (PMID 34070840, 2021). "Results from both the TCGA and CGGA dataset suggest that the expression of CALD1, CALML4 and CALML6 was higher in WHO grade III glioma than WHO grade II glioma." (PMID 34070840, 2021). "However, in the CGGA dataset, only CALD1, CALML4 and CALML6 were associated with IDH wildtype glioma, and no specific relationship with CALM3, CALM1 and CALM2 expression was noticed." (PMID 34070840, 2021). "CALD1, CALML4 and CALML6 might serve as unfavorable biomarkers in glioma." (PMID 34070840, 2021).
Parkinson disease (1 paper, 2025). A progressive degenerative disorder of the central nervous system characterized by loss of dopamine producing neurons in the substantia nigra and the presence of Lewy bodies in the substantia nigra and locus coeruleus. "Pathway enrichment analysis shows that CALML4 is enriched in neurodegenerative pathways, including those associated with AD, Parkinson’s disease, and neurotrophin signaling." (PMID 40076442, 2025). "Here, we show that CALML4 is enriched in neurodegenerative pathways, including AD (hsa05010), Parkinson’s disease (hsa05012), and neurotrophin signaling (hsa04722)." (PMID 40076442, 2025).
infection (1 paper, 2024). The state of being infected such as from the introduction of a foreign agent such as serum, vaccine, antigenic substance or organism. "The expression of OsCaM (calmodulin) and OsCML4 (calmodulin-like 4) genes was markedly activated in mycorrhizal rice in response to infection, indicating a role for Ca2+-mediated signaling processes in systemic resistance to AM-induced pathogen infection in rice plants." (PMID 38592805, 2024).
CALML4 also shares sentences with these, for which no sentence is quoted: breast carcinoma (1 paper); cancer (1); lung carcinoma (1); nasopharyngeal carcinoma (1); tumor (1).